STPG4 (sperm-tail PG-rich repeat containing 4)
Description:
Maternal factor that plays a role in epigenetic chromatin reprogramming during early development of the zygote. Involved in the regulation of gametic DNA demethylation by inducing the conversion of the modified genomic base 5-methylcytosine (5mC) into 5-hydroxymethylcytosine (5hmC).
Synonyms: GSE; C2orf61; FLJ40172
Tractability: No criterion of Open Targets' tractability assessment is met for any kind of drug.
Gene: Protein-coding gene on chromosome 2 (47,045,538 to 47,155,308, reverse strand). Ensembl gene ENSG00000239605.
Subcellular location: Cytoplasm; Nucleus
Subcellular location (Human Protein Atlas): Nucleoplasm; Cytosol
Pathways (Reactome):
Developmental Biology: Chromatin modifications during the maternal to zygotic transition (MZT)
Gene Ontology:
Molecular function: chromatin binding; histone binding
Biological process: epigenetic programing of male pronucleus
Cellular component: cytoplasm; female pronucleus; germinal vesicle; male pronucleus; nucleus
Genetic constraint (gnomAD): Loss-of-function variants: 27 observed, 23.15 expected, observed/expected ratio (o/e) 1.17, 90% interval 0.86 to 1.61. The upper end of that interval is the gene's LOEUF score, 1.61, which puts it in group 6 of 6, group 1 being the genes least tolerant of losing a copy. Missense variants: 305 observed, 248.04 expected, observed/expected ratio (o/e) 1.23, 90% interval 1.12 to 1.35. Synonymous variants: 114 observed, 91.3 expected, observed/expected ratio (o/e) 1.25, 90% interval 1.07 to 1.46.
Homologues: Orthologues: chimpanzee STPG4 (97% identical), macaque STPG4 (92% identical), dog STPG4 (80% identical), pig STPG4 (77% identical), rabbit STPG4 (76% identical), guinea pig STPG4 (73% identical), mouse Stpg4 (69% identical), rat Stpg4 (69% identical).
Diseases named in the same sentence as STPG4 in open-access papers:
STPG4 is named in the same sentence as 1 disease in open-access papers, as found by Europe PMC text mining. Sharing a sentence is not in itself a finding about the gene and the disease. The quoted sentences say what the papers report.
cancer (1 paper, 2025). A tumor composed of atypical neoplastic, often pleomorphic cells that invade other tissues. "We further co-cultured T9141-transduced T cells with full-length STPG4-transduced cancer cells." (PMID 39931057, 2025).